KIF11 (kinesin family member 11)
Diseases named in the same sentence as KIF11 in open-access papers (continued):
Sharing a sentence is not in itself a finding about the gene and the disease.
meningioma (9 papers, 2019 to 2025). A generally slow growing tumor attached to the dura mater. "KIF11 inhibitors inhibit the growth of meningiomas in xenografted mice by more than 80% and have few blood side effects." (PMID 40964093, 2025). "Upregulated KIF11 is positively related to the WHO grade of meningioma, as well as shorter progression-free survival (PFS)." (PMID 38672404, 2024). "Filanesib and ispinesib are effective inhibitors of KIF11 and have been shown to have antitumor effects in meningiomas." (PMID 38012214, 2023). "A recent report also suggested that high expression of KIF11 was frequently observed in clinically more aggressive tumors in meningioma, and knockdown of KIF11 markedly inhibited cell proliferation." (PMID 33995648, 2021). "Our demonstration that KIF11 mRNA and protein levels increased with meningioma WHO grade and that higher mRNA levels of KIF11 were related to shorter progression-free survival, is consistent with prior literature reports in other cancer types." (PMID 30991738, 2019). "This resulted in a significantly inhibited tumor cell proliferation of KIF11-depleted cells by up to 95% and 71%, respectively, suggesting KIF11 as a promising novel therapeutic target in meningiomas." (PMID 30991738, 2019). "Regarding KIF4A and KIF11, we made similar observations, though the number of meningiomas with more than 50% kinesin-expressing cells further increased in WHO°II and °III tumors." (PMID 30991738, 2019). "In summary, these data support an important functional role of KIF11 for meningioma growth and its use as a novel therapeutic target in clinically aggressive meningiomas." (PMID 30991738, 2019). "It was reported that down-regulation of KIF11 decreased the proliferation of meningioma cells." (PMID 32549756, 2020). "Accordingly, KIF11 was supposed to be the novel therapeutic target of meningioma." (PMID 32549756, 2020). "However, only knockdown of KIF11 resulted in a markedly reduced tumor cell proliferation in Ben-Men-1 cells and the newly established anaplastic NF2-mutated meningioma cell line NCH93, proposing KIF11 as a novel prognostic marker and therapeutic target." (PMID 30991738, 2019). "This analysis revealed that high levels of KIFC1 (p = 0.04; HR 1.84), KIF11 (p = 0.03; HR 1.88), KIF14 (p = 0.03; HR 1.91) and KIF20A (p = 0.01; HR 2.13) were associated with a shorter progression-free survival, suggesting kinesins as novel prognostic factors in meningiomas." (PMID 30991738, 2019). "Taken together, in this study we were able to identify the prognostic and functional role of several kinesin family members of which KIF11 exhibits the most promising properties as a novel prognostic marker and therapeutic target, which may offer new treatment options for aggressive meningiomas." (PMID 30991738, 2019). "Altogether, in this study, we were able to characterize the prognostic and functional role of several kinesin family members of which KIF11 provided the most promising properties as a novel prognostic marker and therapeutic target, which may offer new treatment options for aggressive meningiomas." (PMID 30991738, 2019). "To finally address the question, if differentially expressed kinesin family members have an impact on tumor cell proliferation of meningioma cells, we performed a siRNA-mediated knockdown of KIFC1, KIF4A, KIF11, KIF14 and KIF20A." (PMID 30991738, 2019). "Therefore, we used ten meningioma tissue samples for each WHO grade and stained them for KIFC1, KIF4A, KIF11, KIF14 and KIF20A." (PMID 30991738, 2019). "Therefore, we re-analyzed our previous microarray dataset of benign, atypical, and anaplastic meningiomas (n = 62) and got evidence for differential expression of five kinesins (KIFC1, KIF4A, KIF11, KIF14 and KIF20A)." (PMID 30991738, 2019).
meningioma (continued). "To query if kinesin family members might represent novel molecular therapeutic targets, we re-analyzed our previous microarray data set of benign, atypical and anaplastic meningiomas and identified five differentially expressed kinesins (KIFC1, KIF4A, KIF11, KIF14 and KIF20A)." (PMID 30991738, 2019).
bladder cancer (7 papers, 2015 to 2024). "KIF11 inhibitors were more effective at inhibiting the growth of gemcitabine-resistant bladder cancer cell lines." (PMID 35669725, 2022). "Another research showed that overexpression of KIF11 was related to poor differentiation of bladder cancer." (PMID 32346924, 2020).
clear cell renal cell carcinoma (7 papers, 2020 to 2025). "High expression of KIF11 is associated with the worse prognosis of clear cell renal cell carcinoma." (PMID 34838000, 2021). "SB743921, a specific KIF11 inhibitor, significantly suppressed cell proliferation, migration, and epithelial to mesenchymal transition process, in addition to inducing apoptosis in clear cell renal cell carcinoma, which together indicate the dominant roles of KIF11 in tumor pathogenesis." (PMID 33968780, 2021).
liver cancer (7 papers, 2017 to 2023). An epithelial or non-epithelial malignant neoplasm that arises from the liver. "The exact role of KIF11 in the development of liver cancer needs to be clarified in further research." (PMID 33490265, 2021). "KIF11 is related with the progression and prognosis of liver cancer, and its overexpression has been related to low survival rate of patients with liver cancer." (PMID 33193629, 2020). "In addition to CCNB1, CDK1, CDC45, BUB1B, and CCNA2, we also identified five hub genes in Chinese liver cancer, namely AURKA, KIF11, TOP2A, TPX2, and HMMR, which play a crucial role in regulating the cell cycle." (PMID 34257537, 2021).
lung adenocarcinoma (7 papers, 2021 to 2025). A carcinoma that arises from the lung and is characterized by the presence of malignant glandular epithelial cells. "We have recently found that high KIF11 mRNA expression levels are significantly associated with an unfavorable outcome in patients with lung adenocarcinoma." (PMID 39000337, 2024). "As previously observed in lung adenocarcinoma cells, the dual inhibition (sequential or simultaneous) of KIF11 and BCL2L1 caused significant levels of apoptosis in SCLC-A or SCLC-N cells, resulting in markedly reduced viability." (PMID 39000337, 2024). "In lung adenocarcinoma, KIF11 recruits CDH11 to the cell membrane and is known to bind to CDH11; CDH11 is a known outer membrane protein and contributes to cell metastasis." (PMID 39409999, 2024). "Additionally, lung adenocarcinoma cells highly depend on KIF11 for growth." (PMID 39000337, 2024).
oral cancer (7 papers, 2020 to 2025). "Kayo Daigo found that downregulating KIF11 can hasten apoptosis of oral cancer cells, inhibiting cell proliferation at the same time." (PMID 35140744, 2021).
colon cancer (6 papers, 2008 to 2024). "A low expression level of cyclin A2 halts KIF11 phosphorylation at T927 and causes spindle geometry defects in colon cancer." (PMID 38672404, 2024). "Bioinformatic analysis of the TCGA data set revealed 29 upregulated kinesins in colon cancer, with strong overexpression of KIF11 in cancerous colon tissues compared to normal tissues." (PMID 38939361, 2024). "The top 50 genes that were positively correlated (upregulated DEGs; uDEGs) with KIF11 or KIF14 in colon cancer tissues were determined using TCGA dataset and the UALCAN web-based tool." (PMID 34575892, 2021). "We identified gene expression signatures predicting responsiveness to a Kinesin-5 (KIF11) inhibitor (Kinesin-5i) in cultured colon tumor cell lines." (PMID 19259408, 2008). "NEK9 activates NEK6/7 and phosphorylates KIF11, playing an important role in spindle assembly, whereas an upregulated NEK9/KIF11 axis is related to the metastatic potential of colon cancer cells." (PMID 38672404, 2024). "As in colon cancer, also in PAC the expression of KIF11 and/or KIF14 could be identified as a discrimination marker between patients with better and worse overall survival, independently of other relevant clinical risk factors." (PMID 38939361, 2024). "KIF11, together with KIF14, another kinesin involved in the correct cell division, could be responsible for the pathological genomic instability of colon cancer, and their levels reflect the clinical outcome." (PMID 38939361, 2024).
Intellectual disability (6 papers, 2015 to 2024). "While intellectual disability is often described in the literature on KIF11 mutations, autism spectrum disorder (ASD) and attention-deficit/hyperactivity disorder (ADHD) are only mentioned by a few authors but not thoroughly investigated." (PMID 39359715, 2024). "Intellectual disabilities are frequently associated with KIF11 mutations, while other neurodevelopmental disorders such as ASD and ADHD are less commonly reported." (PMID 39359715, 2024). "Children with a KIF11 mutation are now typically referred for child psychiatric diagnostics primarily due to behavioural problems or intellectual disability." (PMID 39359715, 2024). "However, it's crucial to interpret these numbers cautiously, recognising that more diagnostic testing is likely in children with a KIF11 mutation, often due to associated intellectual disability." (PMID 39359715, 2024). "EG5 disruption is implicated in neuronal development and the phenotype observed in MCLMR adds KIF11 to the long list of genes implicated in intellectual disability." (PMID 25934493, 2015). "We present a case report of an 8-year-old boy with KIF11-associated disorder alongside ADHD and ASD but without intellectual disability." (PMID 39359715, 2024).
type 2 diabetes (6 papers, 2009 to 2024). "Interestingly, one of the gene regions recently found to associate with type 2 diabetes contains KIF11 – another kinesin family member." (PMID 19668377, 2009). "Notably, genetic variants in KIF11 have also been identified in patients with type 2 diabetes and diabetic retinopathy, leading us to hypothesize that KIF11 may also play a pivotal role in the pathogenesis of diabetic retinopathy." (PMID 38666385, 2024). "Genome-wide association studies (GWAS) in populations of European ancestry have mapped a type 2 diabetes susceptibility region to chromosome 10q23.33 containing IDE, KIF11 and HHEX genes (IDE-KIF11-HHEX), which has also been replicated in Chinese populations." (PMID 22506066, 2012).
brain tumor (5 papers, 2009 to 2024). "Besides PRUNE_1, the other five genes (i.e., KIF11, KIF14, ASPM, CDK6, and ATR) have been reported as mutated in hereditary MCPH and overexpressed in primary brain tumors (e.g., MB)." (PMID 34745995, 2021). "Our results suggest that KIF11 inhibitors, when able to permeate the blood-brain-barrier, could represent an interesting class of anticancer drugs with low neurotoxic effects in the treatment of brain tumors." (PMID 19545421, 2009). "We found KIF11 overexpressed in a Discovery Cohort of 10 patient tumors, 8 tumor cell lines of ATRT, compared to 10 normal brain tumor tissues." (PMID 34079014, 2021). "Notably, genes downregulated at P14, such as Kif11 and HMGB2, exhibited significant enrichment across all pediatric brain tumor groups, suggesting the importance of astrocytic gene repression during cerebellar development to these tumor subtypes." (PMID 38256095, 2024).
gallbladder cancer (5 papers, 2021 to 2025). "The other point of interest of the present study is that we combined bioinformatics methods and traditional biological experiments to explore the function of KIF11 in gallbladder cancer." (PMID 33613109, 2021). "We analyzed the differentially expressed genes and the correlation between these genes with MKI67, and showed that KIF11 is one of the major upregulated regulators of proliferation in gallbladder cancer (GBC)." (PMID 33613109, 2021). "First, the findings of this study clearly demonstrated that KIF11 promotes cell proliferation of gallbladder cancer cell through ERBB2/PI3K/AKT signaling pathway." (PMID 33613109, 2021). "Second, several bioinformatic tools were used to help us to better understanding the biological function and mechanism of KIF11 in gallbladder cancer." (PMID 33613109, 2021). "Ten gallbladder cancer samples were divided into two groups according to the median value of KIF11 mRNA level and then differentially expressed gene analysis was performed." (PMID 33613109, 2021). "Quantitative PCR and western blot showed that KIF11 is also upregulated in gallbladder cancer cells." (PMID 33613109, 2021). "First, KIF11 is one important driver in gallbladder cancer development." (PMID 33613109, 2021). "In this study, we examined for the first time the effects of KIF11 in gallbladder cancer." (PMID 33613109, 2021). "In gallbladder cancer (GBC), KIF11 facilitated tumor growth via the ERBB2/PI3K/Akt signaling pathway, and the histone acetylation modification (H3K27ac) positively modulated KIF11 expression." (PMID 38433242, 2024). "Differentially expressed analysis showed that EP300, a major histone acetyltransferase modifying H3K27ac signal, is highly expressed in gallbladder cancer and correlation analysis illustrated that EP300 is positively related with KIF11 in almost all the cancer types." (PMID 33613109, 2021).
leukemia (5 papers, 2012 to 2024). A malignant (clonal) hematologic disorder, involving hematopoietic stem cells and characterized by the presence of primitive or atypical myeloid or lymphoid cells in the bone marrow and the blood. "For example, 17p loss increases resistance to seven different drugs in leukaemia (LAML) and five of these target cell cycle/mitotic regulators (KIF11, CDK2/7/9, WEE1, PLK1, microtubules)." (PMID 31974379, 2020).
melanoma (5 papers, 2016 to 2022). A malignant, usually aggressive tumor composed of atypical, neoplastic melanocytes. "In summary, 294 DEGs between the primary and metastatic skin cutaneous melanoma samples were screened, and four hub genes, CDK1, FOXM1, KIF11, and RFC4, were identified that may be associated with the metastasis of melanoma." (PMID 35906389, 2022). "The results showed that three hub genes (CDK1, KIF11 and RFC4) were significantly upregulated in metastatic melanoma tissues compared in primary melanoma tissues." (PMID 35906389, 2022). "Taking probe cg05302035 as an example, KIF11 was hypomethylated in LUAD, PTCC, and melanoma compared with normal tissue, and the hypomethylation status was related to survival probability." (PMID 36742345, 2022).
retinal disease (4 papers, 2016 to 2025). "Given that KIF11 gene mutations have been identified in several retinal diseases, it is tempting to speculate that gene therapy might be a promising strategy for the treatment of KIF11‐associated retinal diseases." (PMID 38666385, 2024). "Furthermore, it will be critically important to continue investigations using clinical samples to explore the involvement of KIF11 UFMylation in retinal diseases." (PMID 38666385, 2024). "This connection warrants further exploration, as understanding the involvement of KIF11 in such common and debilitating conditions could reveal notable insights into the underpinnings of retinal diseases and open new avenues for diagnostic and therapeutic strategies." (PMID 38666385, 2024).
thyroid cancer (4 papers, 2023 to 2025). "Lastly, Eg5 appears to have developed into a diagnostic and prognostic tool for thyroid carcinoma: patients with the highest KIF11 levels had the worst clinical pathological features (T stage and intraglandular dissemination)." (PMID 38939361, 2024). "Cell experiments demonstrate that knocking out KIF11 can inhibit cell proliferation (thyroid cancer cells: TPC-1 and KTC-1 cell lines), promote apoptosis, and induce cell cycle arrest." (PMID 39135992, 2024). "Recent research findings indicate that suppressing KIF11 significantly inhibits thyroid cancer cell proliferation while promoting apoptosis within these cells, highlighting the potential of targeting KIF11 for effective thyroid cancer treatment." (PMID 41462522, 2025). "KIF11 inhibition suppressed thyroid cancer cell proliferation, triggering the apoptotic pathway." (PMID 38939361, 2024). "Immunohistochemistry results show abnormal expression of proteins such as FKBP5, CENPF, CX26, KIF11, PTK7, which are associated with poor prognosis in thyroid cancers with intraglandular dissemination, offering potential guidance for specific targeted therapy in the future." (PMID 39135992, 2024).
cervical cancer (3 papers, 2021 to 2025). A primary or metastatic malignant neoplasm involving the cervix. "On the other hand, the KIF11 protein plays a vital role in cell-cycle regulation and it has been implicated in the tumorigenesis and progression of various cancers, except in cervical cancer." (PMID 41516135, 2025). "Then, the top 40 hub genes were conducted to evaluate the expression and prognostic values of cervical cancer and 7 upregulated (BUB1, CCNB1, CDK1, AURKB, KIF11, PBK, NUSAP1) and 1 downregulated (ESR1) hub genes were selected to have significant values as biomarkers." (PMID 33682613, 2021). "After combination of the expression pattern and survival analysis, eight upregulated hub gens (CCNB1, BUB1, CDK1, AURKB, KIF11, PBK and NUSAP1) stood out with dramatical upregulation in cervical cancer and were significantly correlated with good prognosis of cervical cancer (P < 0.05)." (PMID 33682613, 2021).
liver cirrhosis (3 papers, 2017 to 2024). "Moreover, the KIF11 expression level was strongly associated with TNM stage and liver cirrhosis, and Cox regression analysis showed that KIF11 was an independent factor for overall survival." (PMID 33490265, 2021).
neutropenia (3 papers, 2013 to 2021). A decrease in the number of neutrophils found in the blood. "Neutropenia is the most common adverse effect presented by KIF11 inhibitors already analyzed on clinical trials." (PMID 34548908, 2021). "However, despite the great results obtained in preclinical studies using KIF11 inhibitors there are still some problems being faced in clinics, like the occurrence of neutropenia being the dose-limiting factor and the emergence of resistance." (PMID 34548908, 2021).
pancreatic adenocarcinoma (3 papers, 2020 to 2025). "Similarly, in pancreatic adenocarcinoma, elevated KIF11 expression has been linked to adverse clinical outcomes." (PMID 40075652, 2025). "We also applied transcriptomics of pancreatic adenocarcinoma patients and healthy donors using publicly available datasets to assess the expression levels and prognostic impact of KIF11 and KIF14 mRNAs." (PMID 34208606, 2021). "Through data analysis with the Cancer Genome Atlas (TCGA), we then identified elevated KIF11 and KIF14 mRNA levels of pancreatic adenocarcinomas as independent predictors of reduced survival." (PMID 34208606, 2021). "Functional enrichment analyses were further performed to predict biological functions and pathways related to KIF11 or KIF14, which may possibly impact the course of pancreatic adenocarcinoma." (PMID 34208606, 2021).
sarcoma (3 papers, 2017 to 2023). A usually aggressive malignant neoplasm of the soft tissue or bone. "KIF11 kinesin, which is overexpressed in tetraploid sarcoma cells, was shown to be involved in regulation of cell migration." (PMID 28035071, 2017). "CDK1, KIF11, AURKB, MAD2L1, BUB1B and CCNB2 were highly expressed in sarcoma and were markedly related to worse OS." (PMID 34838000, 2021). "Interestingly, our analyses found that both KIF11 and KIF15 were highly expressed across all the various sarcomas included in the portal." (PMID 37894278, 2023). "Indeed, we observed by immunofluorescence that a number of mitotic proteins, such as KIF11, KIF23 and PLK1 were overexpressed in interphase in sarcoma cell lines (data not shown)." (PMID 28035071, 2017).